KAT2B (lysine acetyltransferase 2B)
Diseases named in the same sentence as KAT2B in open-access papers (continued):
Sharing a sentence is not in itself a finding about the gene and the disease.
leukemia (7 papers, 2004 to 2024). A malignant (clonal) hematologic disorder, involving hematopoietic stem cells and characterized by the presence of primitive or atypical myeloid or lymphoid cells in the bone marrow and the blood. "Nonetheless, our study revealed a compensatory relationship between KAT2A and KAT2B in maintaining H3K9ac, allowing leukemia cells to escape the single KAT2 gene targeting." (PMID 38394203, 2024). "Targeting the GCN5 family H3K9 acetyltransferases (including KAT2A and KAT2B) in the mammalian genome, thus represents a promising strategy for leukemia therapy." (PMID 38394203, 2024). "We found that depletion of either Kat2a or Kat2b individually minimally affected the cellular survival (red and green populations), H3K9ac level, and the LSC marker c-Kit expression (red and green groups) in the leukemia cells." (PMID 38394203, 2024). "Whilst we did not observe up-regulation of Kat2b in leukemia cells, we did not specifically look for it in normal hematopoiesis, and cannot exclude that it may explain the difference between healthy and leukemic blood cells." (PMID 31985402, 2020).
colorectal cancer (6 papers, 2019 to 2025). A primary or metastatic malignant neoplasm that affects the colon or rectum. "KAT2B decreases the acetylation of BRCA2 to enhance the sensitivity of cancer cells in colorectal cancer." (PMID 39901144, 2025). "KAT2B was found to inhibit the progression of tumors including esophageal cancer and colorectal cancer." (PMID 39901144, 2025). "This acetylation step, mediated by lysine acetyltransferase 2B (KAT2B), occurs at ATIC Lys 266, dramatically inhibits ATIC activity, and inversely correlates with colorectal cancer (CRC) tumor growth in vitro and in vivo, and acetylation of ATIC is downregulated in human CRC samples." (PMID 36750554, 2023).
diabetes (5 papers, 2015 to 2022). "Specifically, it should be noted that ABCG1, ABCA1 and ACSL3 were negatively, while KAT2B positively, associated with all signatures of statin use, CpG methylation and diabetes risk/status." (PMID 32612641, 2020). "HUANG_FOXA2_TARGETS_UP comprises 45 genes, some of which have been suggested to be implicated in the development of diabetes, such as KAT2B and TNFAIP3." (PMID 28744461, 2017). "Administration of a small molecule KAT2B antagonist lowered circulating blood glucose concentrations in insulin resistance, suggesting that this enzyme may be a useful target for diabetes treatment." (PMID 36005139, 2022).
esophageal squamous cell carcinoma (5 papers, 2016 to 2024). Esophageal squamous cell carcinoma (ESCC) is a type of esophageal carcinoma (EC) that can affect any part of the esophagus, but is usually located in the upper or middle third. "At present, most studies tend to support the tumor suppressive effect of KAT2B, which is downregulated in esophageal squamous cell carcinoma (ESCC) and intestinal-type gastric cancer compared to adjacent non-tumor tissues." (PMID 34149798, 2021).
glioma (5 papers, 2007 to 2025). A benign or malignant brain and spinal cord tumor that arises from glial cells (astrocytes, oligodendrocytes, ependymal cells). "We observed that the expression of KAT2B was enhanced in clinical glioma samples." (PMID 35432536, 2022). "In the current work, we found that the expression of KAT2B was enhanced in clinical glioma samples." (PMID 35432536, 2022). "Next, we were interested in the correlation of KAT2B with ferroptosis in glioma cells." (PMID 35432536, 2022).
liver cancer (5 papers, 2018 to 2023). An epithelial or non-epithelial malignant neoplasm that arises from the liver. "KAT2B linked with the occurrence of tumor cells ferroptosis in liver cancer." (PMID 34130593, 2021).
medulloblastoma (5 papers, 2020 to 2023). A malignant, invasive embryonal neoplasm arising from the cerebellum. "Lysine acetyltransferase 2B (PCAF) is an important cofactor of the Hedgehog-GLI (Hh-GLI) signaling pathway, which is responsible for medulloblastoma pathogenesis." (PMID 34066495, 2021).
atherosclerosis (4 papers, 2020 to 2022). A disease characterized by the build-up of fatty material and calcium deposition in the arterial wall resulting in partial or complete occlusion of the arterial lumen. "Considering no direct evidence connecting CD38, PTPN11, NOTCH1, TLR7, and KAT2B with the pathogenesis of MMD, their roles in atherosclerosis may also provide a new perspective and direction for future research on the molecular targeted therapy of MMD." (PMID 36605987, 2022).
osteoporosis (4 papers, 2019 to 2025). A condition of reduced bone mass, with decreased cortical thickness and a decrease in the number and size of the trabeculae of cancellous bone (but normal chemical composition), resulting in increased fracture incidence. "The KAT2B/H3K27ac/SRSF1 axis shows the dual effect of inhibiting osteoblast differentiation and promoting osteoclast differentiation, thus aggravating osteoporosis." (PMID 40153585, 2025).
Hyperglycemia (3 papers, 2018 to 2025). An increased concentration of glucose in the blood. "KAT2B knockdown mice showed a reduction in body weight and hyperglycemia in comparison to control mice." (PMID 29500370, 2018).
melanoma (3 papers, 2022 to 2025). A malignant, usually aggressive tumor composed of atypical, neoplastic melanocytes. "HATs such as KAT1 (HAT1) and KAT2B (PCAF) have been identified to confirm the epigenetic impact in melanoma, So that increasing the activation of the AKT signaling pathway gives rise to MAPKi resistance." (PMID 36224606, 2022). "Among them, 6 genes (NPTX1, AUTS2, RPS6KA2, KAT2B, MYO5A and HMG20B) were simultaneously downregulated in the melanoma samples compared with the noncancerous samples in GSE31909 and GSE35388 microarray data." (PMID 37384727, 2023).
myocardial infarction (3 papers, 2016 to 2021). Gross necrosis of the myocardium, as a result of interruption of the blood supply to the area, as in coronary thrombosis. "On the other hand, however, a study on KAT2B showed that this HAT was essential for inflammation-induced post-ischemic arteriogenesis, suggesting that activation of KAT2B can aid in recovery after ischemic events such as stroke or myocardial infarction." (PMID 27231488, 2016).
Obesity (3 papers, 2018 to 2022). Accumulation of substantial excess body fat. "In conclusion, our data revealed that common variants of ARID1A and KAT2B are associated with increased susceptibility to overweight/obesity in Indian urban adolescents." (PMID 29500370, 2018). "In conclusion, our study suggests a potential role of ARID1A and KAT2B genes in the development of obesity in adolescents and provides leads for further investigations." (PMID 29500370, 2018).
cardiomyopathy (2 papers, 2018 to 2022). A disease of the heart muscle or myocardium proper. "Patients from family A are also homozygous for a missense mutation of lysine acetyltransferase 2B (KAT2B) and the expanded pathologic spectrum, including cardiomyopathy and renal problems." (PMID 35269756, 2022). "Family A, which was characterized by additional cardiomyopathy and SRNS, exhibited another potentially damaging homozygous mutation in lysine acetyltransferase 2B (KAT2B)." (PMID 29768408, 2018). "Our study implicates KAT2B as a susceptibility gene for steroid-resistant nephrotic syndrome (SRNS) and cardiomyopathy and emphasizes the importance of protein acetylation in kidney and heart function." (PMID 29768408, 2018).
cholangiocarcinoma (2 papers, 2024 to 2025). A carcinoma that arises from the intrahepatic biliary tree (intrahepatic cholangiocarcinoma) or from the junction, or adjacent to the junction, of the right and left hepatic ducts (hilar cholangiocarcinoma). "In summary, the current study provides novel evidence that KAT2B plays an important tumor suppressive role in cholangiocarcinoma through interaction with SP1 to enhance the expression of NF2 which leads to subsequent inhibition of oncogenic YAP." (PMID 38641672, 2024). "KAT2B exhibits tumor-suppressive roles in cervical, cholangiocarcinoma, and ovarian cancers." (PMID 40495188, 2025). "However, based on our RNA-seq data, the KAT2B/GLI1/BCL2 pathway is not applicable in cholangiocarcinoma." (PMID 38641672, 2024). "While the current study is focused on the effect and mechanism of KAT2B in cholangiocarcinoma, it remains to be determined whether the KAT2B-NF2-YAP signaling pathway identified in CCA may also be applicable to other cancers." (PMID 38641672, 2024).
coronary artery disease (2 papers, 2020 to 2024). "Another study linked KAT2B variants rs3021408 and rs17006625 with an increased risk of coronary artery disease in the Han Chinese population." (PMID 39734414, 2024).
neuroblastoma (2 papers, 2020 to 2024). Neuroblastoma (NB) is the most common solid, extracranial childhood tumor. "On the basis of our findings using the PROTAC degrader GSK-699-1, combined loss of KAT2A/KAT2B reduced neuroblastoma proliferation and induced transcriptional and epigenetic changes that are consistent with TADA2B degradation." (PMID 38820154, 2024). "We report that the acetyltransferase activity of the SAGA complex is required to maintain the oncogenic state in neuroblastoma and that impairing this activity either through TADA2B KO/degradation or through combined loss of KAT2A/KAT2B impairs neuroblastoma cell growth." (PMID 38820154, 2024). "On the basis of our previous data showing that simultaneous KAT2A/KAT2B loss reduced neuroblastoma viability, we hypothesized that the KAT2A/KAT2B PROTAC, GSK-699, may be a pharmacologic intervention for MYCN-amplified neuroblastoma." (PMID 38820154, 2024). "Together, these data suggest that therapeutic targeting of the SAGA complex via degradation of KAT2A and KAT2B may be a therapeutic strategy for MYCN-amplified neuroblastoma." (PMID 38820154, 2024). "To interrogate the possibility that KAT2A and KAT2B are functionally redundant in this context, we used two MYCN-amplified neuroblastoma cell lines, KELLY and NB1, that depend on TADA2B but have high and low KAT2B expression, respectively." (PMID 38820154, 2024). "The SAGA acetyltransferase complex is required to promote neuroblastoma growth and is targetable with a KAT2A/KAT2B PROTAC." (PMID 38820154, 2024). "Further, the impact of pharmacologic degradation of KAT2A/KAT2B strongly correlated with the impact of TADA2B degradation, supporting the importance of the SAGA complex in maintaining MYCN-amplified neuroblastoma." (PMID 38820154, 2024). "We then knocked out KAT2B with two distinct sgRNAs and found that KELLY cells were now more sensitive to KAT2A degradation, indicative of functional redundancy between these two paralogs in neuroblastoma." (PMID 38820154, 2024).
rheumatoid arthritis (2 papers, 2023 to 2024). A chronic, systemic autoimmune disorder characterized by inflammation in the synovial membranes and articular surfaces. "Consistent with our findings, the HDAC KAT2B gene is also upregulated in PBMCs from rheumatoid arthritis patients, and its overexpression increases histone H4 acetylation on the enhancer of MHC class I promoters." (PMID 38255677, 2023).
allergic rhinitis (1 paper, 2020). Inflammation of the nasal mucous membranes caused by an IgE-mediated response to external allergens. "The regulation of miR-92a-3p modified the transcription of KAT2B and PARP1, which played an important role in the development of combined allergic rhinitis and asthma syndrome." (PMID 31924195, 2020).
anxiety disorder (1 paper, 2024). A category of psychiatric disorders which are characterized by anxious feelings or fear often accompanied by physical symptoms associated with anxiety. "In the earlier lineage, risk genes associated with abnormal brain morphology (AGMO) and anxiety disorders (KAT2B) were highly expressed." (PMID 39363111, 2024).
autism (1 paper, 2021). Persistent deficits in social interaction and communication and interaction as well as a markedly restricted repertoire of activity and interest as well as repetitive patterns of behavior. "We found differential expression of autism-relevant genes in our DE gene list that are also associated with cell adhesion (Dscam, Reln) or gene regulation (Kat2b, Kmt2c, Med13/Med13l, Tbl1xr1, Ubn2)." (PMID 33757588, 2021).
brain tumors (1 paper, 2023). "However, KAT2B was shown as a positive co-factor of the Hedgehog–Gli signaling pathway in brain tumors, and KAT2B silencing attenuated the tumor-forming capacity of neural stem cells in vivo, suggesting that the KAT2B role in stem cell biology might be highly context-dependent." (PMID 36674511, 2023).
Burkitt lymphoma (1 paper, 2019). A rare form of malignant mature B-cell non-Hodgkin lymphoma. "We also examined expression of GCN5 (KAT2A) and PCAF (KAT2B) in lymphoma cell lines in the Cancer Cell Line Encyclopedia (CCLE) database and again observed that GCN5 (KAT2A) mRNA levels are elevated in many different cancer cell lines including human Burkitt lymphoma (BL) cells." (PMID 31645904, 2019).
cervical tumor (1 paper, 2021). "KAT2B may be a new cervical tumor-suppressor gene, which is closely concerned with poor prognosis of patients, and under negative regulation by miR-93-5p." (PMID 34130593, 2021).
co-infection (1 paper, 2025). "Regarding the co-infection of cells by E. coli and S. aureus, the unique genes of ES2 are DZIP1 and SMTNL2; the unique genes of ES3 are ALDH4A1, DNASE1L1, FAM227A, and KAT2B; and ES1 has 143 unique genes." (PMID 40771952, 2025).
cognitive deficits (1 paper, 2023). "While KAT2B activation is beneficial for memory in normal rodents, knockout or inhibition of KAT2B attenuates AD-like cognitive deficits in Aβ-treated rodents." (PMID 36894612, 2023).
COVID-19 (1 paper, 2022). A disease caused by infection with severe acute respiratory syndrome coronavirus 2. "While the molecular mechanisms of KAT2B-dependent regulation of the TGFβ pathway in COVID-19 remain to be understood we surmise host variants in KAT2B may modify disease progression and severity following SARS-CoV-2 infection." (PMID 36143338, 2022).
esophageal cancer (1 paper, 2025). A primary or metastatic malignant neoplasm involving the esophagus. "KAT2B can increase the acetylation level of Fascin in to suppress tumor growth in esophageal cancer." (PMID 39901144, 2025).
head and neck squamous cell carcinoma (1 paper, 2024). A squamous cell carcinoma that arises from any of the following anatomic sites: lip and oral cavity, nasal cavity, paranasal sinuses, pharynx, larynx, and salivary glands. "Moreover, it was also reported that most Kcr regulators, including DPF2, KAT2B, and HDAC2–3, were significantly dysregulated in patients with head and neck squamous cell carcinoma (HNSCC); this observation positively correlated with lymph-node metastasis, T stage, and histologic grade." (PMID 38315203, 2024).
lymphoma (1 paper, 2019). A malignant (clonal) proliferation of B- lymphocytes or T- lymphocytes which involves the lymph nodes, bone marrow and/or extranodal sites. "Examination of CRISPR screen data revealed some dependence of leukemia and lymphoma cell lines on either or both KAT2A (GCN5) and KAT2B (PCAF)." (PMID 31645904, 2019).
multiple myeloma (1 paper, 2016).
oral cancers (1 paper, 2019).
renal carcinoma (1 paper, 2025). A carcinoma arising from the epithelium of the renal parenchyma or the renal pelvis. "For example, in renal cancer organoid models, epigenetic silencing of KAT2B through promoter hypermethylation was shown to drive metabolic reprogramming and tumor progression; restoration of KAT2B or inhibition of its downstream target of FASN-suppressed organoid growth." (PMID 41440207, 2025).
Sepsis (1 paper, 2025). Sepsis is defined as life-threatening organ dysfunction caused by a dysregulated host response to infection. "KAT2B, a member of the GNAT protein family, plays various roles in the development of both tumors and inflammatory diseases, such as sepsis, through acetylation." (PMID 39721014, 2025).
yang deficiency (1 paper, 2022). Yang deficiency is a concept from traditional Chinese medicine. "The symptomatic gene targets for Yang deficiency (KAT2B, NFKB2, CREBBP, GTF2H3) or Yin deficiency (JUNB, JUND, NGLY1, TNF, RAF1, PPP1R15A) were potentially discovered." (PMID 35341155, 2022). "In particular, KAT2B, NFKB2, CREBBP, and GTF2H3 were the key contributive targets for the Yang deficiency group." (PMID 35341155, 2022). "KAT2B, NFKB2, CREBBP, and GTF2H3 are represented as candidate markers for Yang deficiency." (PMID 35341155, 2022).